IL33 (interleukin 33)
Diseases named in the same sentence as IL33 in open-access papers (continued):
Sharing a sentence is not in itself a finding about the gene and the disease.
diabetes (continued). "Taken together, our results suggest that deletion of IL-33 worsens diabetes-induced reduction of retinal electrophysiological functions." (PMID 37671525, 2023). "Lately, increasing studies have reported that IL-33 is closely related to heart-related diseases, diabetes, kidney disease, and autoimmune development." (PMID 35096114, 2022). "Similar to a previous study, IL-33 was significantly positively correlated with sST2 levels in patients with diabetes (r = 0.44)." (PMID 36684579, 2022). "We have shown recently that the application of exogenous IL-33 given from the beginning of MLD–STZ diabetes induction attenuates the development of diabetes, by increasing the presence of regulatory FoxP3+ ST2+ cells." (PMID 34803672, 2021). "We have shown previously that IL-33 exhibit complete protection of MLD–STZ diabetes if given from the beginning of the disease induction." (PMID 34803672, 2021). "In the presence of diabetes, the basal secretion of IL-1β, IL-27, IL-33, and SDF-1 is augmented while that of IL-10, IL-12, and IL-8 was downregulated." (PMID 34566972, 2021). "TG mice treated with IL-33 (12–18 days of experiment) were more resistant to MLD–STZ–induced diabetes as evaluated by all metabolic parameters, particularly in the glucose tolerance test, compared to the TG mice without IL-33 treatment." (PMID 34803672, 2021). "The addition of IL-33 in TG mice further attenuated diabetes even when administered later, after the onset of hyperglycemia, 12–18 days after disease induction." (PMID 34803672, 2021). "A special mention is related to IL-33, cytokine with a dual role in diabetes, either as a proinflammatory and anti-inflammatory agent, dependent on the experimental model used." (PMID 32824505, 2020). "Our study has shown that IL-33 prevents MLD-STZ diabetes induction if given at the time of disease induction." (PMID 30498495, 2018). "To extend this finding for possible relevance in spontaneous diabetes, we showed that IL-33 attenuate insulitis in prediabetic NOD mice." (PMID 30498495, 2018). "As Th2 immune response has a protective role in pathogenesis of diabetes, it is possible that one of potential mechanisms of attenuation of the disease mediated by IL-33 is directing immune response toward Th2." (PMID 30498495, 2018). "The aim of this study was to investigate the effect of exogenous IL-33 in multiple low dose streptozotocin (MLD-STZ) induced diabetes and to delineate its role in the induction of protective Tregs in an autoimmune attack." (PMID 30498495, 2018). "In our further analysis, we wanted to examine the effect of exogenous IL-33 on the development of mononuclear infiltrates in spontaneous diabetes NOD mice." (PMID 30498495, 2018). "We provide evidence that exogenous IL-33 completely prevents the development of T cell mediated inflammation in pancreatic islets and consecutive development of diabetes in C57BL/6 mice by facilitating the induction Treg cells." (PMID 30498495, 2018). "Our study also showed that the exogenous IL-33 leads to the expansion of CD11c+IL-2+ cells and increased number of CD4+Foxp3+ST2+ immunoregulatory cells that suppress the development of diabetes in mice treated with IL-33 during the induction of the disease." (PMID 30498495, 2018). "The multivariate Cox analysis showed that the presence of diabetes mellitus, smoking, and proteinuria and levels of haemoglobin, Hs-CRP, IL-33, and ST2 were associated with the risk of CV events." (PMID 28614418, 2017). "Multivariate Cox analysis showed that the presence of diabetes mellitus, smoking, and proteinuria and haemoglobin, Hs-CRP, IL-33, and ST2 were associated with the risk of CVE." (PMID 28614418, 2017). "We then confirmed that decreased REG3A expression was possibly due to decreased IL-33 in diabetic skin wounds, as the administration of IL-33 into the dorsal skin of diabetes restored RegIIIγ expression." (PMID 27830702, 2016).
diabetes (continued). "The reduction of cutaneous REG3A, possibly as a consequence of decreased IL-17-induced IL-33 caused by hyperglycaemia, will therefore lead to excessive production of TLR3-mediated pro-inflammatory cytokines observed in diabetes after skin trauma." (PMID 27830702, 2016). "Patient age, weight, BMI, BSA, diabetes, GFR, SBP, phosphate and urine microalbumin were significantly associated with IL-33 levels in the UVA." (PMID 26544186, 2015). "UVA of factors significant to high IL-33 levels included estimated glomerular filtration rate (eGFR), while diabetes mellitus, serum phosphorus, microalbuminuria and age also remained significant in the multivariate analysis." (PMID 26544186, 2015). "In relation to diabetes, IL33 exerted protective effects in an animal model of obese diabetic mice (ob/ob) reducing adiposity, fasting plasma glucose and improving glucose tolerance and insulin resistance." (PMID 22104207, 2011). "STZ-induced diabetes was associated with a significant decrease in the anti- inflammatory cytokine IL-10 and an increase in the proinflammatory cytokines CXCL-1, IFN-γ, IL-6, IL-18, and IL-33." (PMID 40649891, 2025). "Induction of diabetes significantly reduced the number of cone photoreceptor cells in WT and Il33−/− mice after 6 months of diabetes, although the reduction was more profound in Il33−/− diabetic mice." (PMID 37671525, 2023). "The expression of IL-33 in Müller cells increased during diabetes." (PMID 37671525, 2023). "Our results suggest that diabetes-mediated retinal neuronal damage is accelerated in Il33−/− mice." (PMID 37671525, 2023). "However, after 6 months of diabetes, Il33−/− retinas expressed significantly lower levels of Glul and higher levels of Bdnf, Cntf, Fgf2 and Ngf compared with the levels in WT retinas." (PMID 37671525, 2023). "To understand the role of IL-33 in DR, we induced diabetes in WT and Il33−/− mice by STZ injection." (PMID 37671525, 2023). "However, 6 months after the induction of diabetes, the expression levels of Ccl2, Il1b, Il6, Tnf, Tgfb and Inos (Nos2) were significantly higher in the Il33−/− retina than in the WT retina." (PMID 37671525, 2023). "Intriguingly, the increase in IL-33 levels in DN is only associated with diabetes but not with kidney injury." (PMID 36776877, 2023). "Collectively through distinct mechanisms, IL-33 potentially functions as a nuclear effector to maintain and regulate inflammatory cytokine expression and clearance of glutamate in the retina during diabetes." (PMID 37671525, 2023). "In other words, normal or increased concentrations of IL-33 prevent the onset of diabetes." (PMID 36614933, 2022). "However, IL-33 treatment was much less effective if given after the diabetes onset or if applied in NOD mice." (PMID 34803672, 2021). "The authors hypothesized that sST2 not only is a biomarker but also may contribute to the pathogenesis of diabetes via IL-33 interactions." (PMID 32089758, 2020). "Given the widespread diffusion of renal diseases and diabetes worldwide and, consequently, the high impact such diseases have on society and on healthcare systems, we performed a literature review about the IL-33/ST2 axis involvement in diabetic kidney disease or related nephropathy." (PMID 30769901, 2019). "Finally, in order to show relevance of our findings for the development of “spontaneous” diabetes, we looked at the possibility that exogenous IL-33 alter the onset of insulitis in prediabetic NOD mice." (PMID 30498495, 2018). "Taken together these data suggested that in vivo treatment of IL-33 may have beneficial effects in MLD-STZ diabetes by promoting Tregs and in particular ST2+ Tregs producing IL-10 and possibly IL-5 and/or IL-13." (PMID 30498495, 2018). "As it has been shown recently that Type 1 interferon inhibits IL-10 signaling and development of diabetes in NOD mice which is promoted by IL-33, the mechanism may be similar." (PMID 30498495, 2018).
diabetes (continued). "Moreover, an attempt to therapeutically apply IL-33, 6 and 12 days after diabetes induction had significant effects on the development of clinical and laboratory signs of the disease." (PMID 30498495, 2018). "In this paper we describe the experiments showing that exogenous IL-33 may prevent development of MLD-STZ diabetes in C57BL/6 mice and significantly attenuate development of insulitis in prediabetic NOD mice." (PMID 30498495, 2018). "Associations of IL33 polymorphisms in patients with premature CAD and diabetes mellitus." (PMID 28045954, 2017). "In mice with diabetes mellitus, the lower expression of IL-33 may exaggerate ischemia/reperfusion-induced myocardial injury." (PMID 27699084, 2016). "The exact role of ST2/IL-33 axis remains mysterious in diabetes." (PMID 26989334, 2016). "Diminished eGFR, age, diabetes, serum phosphorus and microalbuminurea demonstrate significant relationship with elevated IL-33 levels, supporting the possible pathognomonic role of IL-33 in the cardiovascular burden in RTR." (PMID 26544186, 2015). "However, recent studies have highlighted the development of multiplex assays to measure low abundance IL-33 in serum or plasma and warrant further investigation in the context of diabetes and CVD." (PMID 23112853, 2012). "It is thus possible that sST2 is not only a biomarker but may contribute to the pathogenesis of diabetes via IL-33 interactions." (PMID 23112853, 2012). "In states of oxidative stress as in diabetes increased expression of endothelin 1 has been found paradoxically to restore diastolic dysfunction and endothelin 1 is a known inducer of sST2 expression and inhibitor of IL-33 signaling through p38 MAPK." (PMID 22104207, 2011). "From this point of view IL-33/ST2 pathway might prove to be a crucial pathway in balancing the intensity of inflammation in diabetes." (PMID 22104207, 2011). "In addition, their study revealed that in nondiabetic patients, IL-33 was associated with a protective lipid profile, whereas no such association was found in patients with diabetes." (PMID 39171751, 2024). "The addition of IL-33 potentiated the survival of β cells and attenuated diabetes even when administered later, after the onset of hyperglycemia (12–18 days), suggesting that protection from apoptosis and immunoregulation by IL-33 may attenuate type 1 diabetes." (PMID 34803672, 2021). "Thus, we showed that exogenous IL-33 attenuates MLD-STZ diabetes induction." (PMID 30498495, 2018). "Associations of IL33 polymorphisms in patients with premature CAD without diabetes mellitus." (PMID 28045954, 2017). "A recent clinical study by Caner and colleagues investigated the association between IL-33 and DN by analyzing the serum levels of IL-33 from a healthy group, a diabetes mellitus (DM) group without any known renal diseases, and a DM group with microalbuminuria (MA)." (PMID 28387719, 2017). "Increased levels of sST2 during diabetes may impair the protective effects of IL-33." (PMID 23112853, 2012). "For instance, study examined IL-33/ST2L signaling pathway in DKD used flow cytometry to assess apoptosis in glomerular endothelial cells, showing that in diabetes mice, IL-33 therapy decreased endoplasmic reticulum stress and cellular death." (PMID 39702603, 2024). "A prior report demonstrated that IL-33 alleviates hepatic steatosis in high-fat diet-induced murine MAFLD, while another demonstrated a harmful role in the face of diabetes and MASH." (PMID 39228797, 2024). "Murine models reveal that IL-33 drives the expansion of highly suppressive GATA3+CTLA4+ Tregs that, in turn, prevent the onset of diabetes." (PMID 39704171, 2024). "Thus, deletion of IL-33 in the retina during diabetes may disrupt glutamate clearance, neurotransmitter recycling and the secretion of neurotrophins, and this leads to lower ERG a- and b-wave amplitudes, retinal neuronal thickness, and numbers of photoreceptors and ganglion cells during diabetes." (PMID 37671525, 2023).
diabetes (continued). "Interestingly, elevated levels of ST2 are associated with increased risk of diabetes mellites in both non-diabetic and prediabetic patient populations, whereas IL-33 may have protective roles in glycemic control." (PMID 33755703, 2021). "Secretion of IL-27, IL-1Ra, IL-12, IL-33, IL-9, and SDF-1 was increased under diabetes conditions with increased Th9 polarization and increased expression of Cox-2 and IDO." (PMID 34566972, 2021). "Because elevated glucose levels are characteristic of diabetes, and we also observed the higher glycated haemoglobin levels in T1D mice compared with the healthy controls, we hypothesized that high glucose might participate in the regulation of IL-33 production induced by IL-17." (PMID 27830702, 2016). "The IL-33/ST2 pathway is involved in various human diseases including asthma, inflammatory bowel disease, diabetes, autoimmune disease and cerebral inflammation." (PMID 27699084, 2016). "The retinal expression of Il33 was then investigated in non-diabetic and diabetic mice (6 months of diabetes) by scRNA-seq, immunohistochemistry and real-time quantitative PCR (RT-qPCR)." (PMID 37671525, 2023). "Some limitations exist in this study, which included that animal model only used male young mice, mice with complications like aging or diabetes have not been studied, and the specific mechanism that lipogenesis mediated IL-33 expression was unrevealed." (PMID 37968698, 2023). "While TLR-induced IL-12 and basal IL-33 secretion was augmented under diabetes condition, this was not seen at the level of Th1 and Th2 polarization." (PMID 34566972, 2021). "This demonstrated the up-regulation of IL-33 in diabetes, but failed to reliably show the usefulness of IL-33 for early diagnosis of DN." (PMID 30769901, 2019). "Exogenous IL-33 showed strong suppressive effects on diabetes induction and no biochemical parameters of the disease onset were noticed." (PMID 30498495, 2018). "The in vivo experiments showed that IL-33, but not IL-36γ, was decreased in a similar expression pattern of RegIIIγ in the skin wounds of T1D mice, as well as patients with diabetes." (PMID 27830702, 2016). "The IL-33/ST2 pathway may participate in the inflammatory and remodeling processes of various tissues during diabetes." (PMID 23112853, 2012). "Delayed application of IL-33 after MLD–STZ diabetes induction was not very effective." (PMID 34803672, 2021). "Since Gal-3 overexpression did not affect regulatory T cells in MLD–STZ diabetes in TG mice, we investigated whether the stability of the islet cells and the possible lower level of diabetogenic effect were affected by IL-33." (PMID 34803672, 2021). "Therefore, diabetes per se upregulates the serum level of IL-33, but it is not suitable to be used for early diagnosis of DN." (PMID 28387719, 2017). "The role of IL-33/ST2 pathway in type I and II diabetes remains vastly unknown today." (PMID 22104207, 2011). "From this point of view, increased levels of sST2 in patients with diabetes and LVDD might be an epiphenomenon of other counteregulatory mechanisms such as endothelin 1 or to signify patients with failure of IL-33-induced cardioprotection, through sST2 acting as a decoy receptor." (PMID 22104207, 2011).
Stroke (45 papers, 2013 to 2025). Sudden impairment of blood flow to a part of the brain due to occlusion or rupture of an artery to the brain. "The association between IL-33 and stroke prognosis was analyzed in a subgroup excluding patients who received acute reperfusion therapy." (PMID 39650246, 2024). "Studies have identified inflammatory markers like CRP, IL-6, and IL-33 as predictors of initial stroke risk and post-stroke prognosis." (PMID 38169754, 2024). "This study demonstrates that lower IL-33 levels are associated with increased stroke severity and poorer prognosis." (PMID 39650246, 2024). "In conclusion, our findings suggest that low IL-33 levels are linked to greater stroke severity and poorer outcomes, reinforcing the potential of IL-33 as a biomarker for predicting adverse prognosis following acute ischemic stroke." (PMID 39650246, 2024). "IL-33 is thought to promote the proliferation of Treg cells because their numbers in the CNS after stroke is decreased in IL-33-deficient mice." (PMID 32174916, 2020). "Secondly, the lack of research objects and the low incidence of recurrent ischemic stroke caused insufficient power for IL‐33 levels to predict stroke recurrence." (PMID 31397082, 2019). "In this study, we found that lower serum IL‐33 levels were associated with worse prognosis and recurrence of first‐ever stroke." (PMID 31397082, 2019). "Our results suggest that the lower level of serum IL-33 is associated with large infarction volume and greater stroke severity in AIS patients." (PMID 27699084, 2016). "Compared to previous studies, this research provides new insights into the prognostic value of low serum IL-33 levels in acute ischemic stroke (AIS) by demonstrating that lower IL-33 levels are associated with increased stroke severity, worse functional outcomes, and higher mortality rates." (PMID 39650246, 2024). "However, IL33 was not increased in proliferating OPCs 48 h after thromboembolic MCAO in mice, This suggests that the acute upregulation of IL33 in OPCs is dependent on the species and/or the underlying stroke model and stroke severity." (PMID 39043661, 2024). "Although IL-17 has these neuroprotective effects, mice treated with IL-33 showed an exacerbation of post-stroke pulmonary bacterial infection associated with greater functional impairment and mortality after 24 hours, suggesting exacerbation of systemic immunosuppression after ischemic stroke." (PMID 35173738, 2022). "We found that lower serum IL-33 was associated with an increased stroke severity in AIS patients." (PMID 27699084, 2016). "Moreover, a substantial subset of these OPCs expressed the snRNAseq predicted, injury-associated markers VIM, across different species and stroke models, while the upregulation of the injury marker IL33 in OPCs was restricted to filament-based MCAO infarctions in rats." (PMID 39043661, 2024). "Furthermore, the level of serum IL-33 was associated with the severity of stroke." (PMID 27699084, 2016). "IL-33 is an important endogenous regulator in stroke, which can downregulate the level of pro-inflammatory cytokines, inhibit apoptosis and autophagy, and exert anti-inflammatory effects on brain edema caused by ICH." (PMID 40289984, 2025). "Previous studies have shown that IL-33 can reduce astrocyte activation in the ischemic penumbra following stroke." (PMID 40764944, 2025). "IL-33 serum levels were found to decrease with increasing stroke severity as defined by NIHSS scores and lesion size." (PMID 39650246, 2024). "IL-33 serum levels were inversely correlated with stroke severity, as measured by the National Institutes of Health Stroke Scale (NIHSS) score and lesion size." (PMID 39650246, 2024). "We previously proved that IL-33 was the mediator for spontaneous lipogenesis to improve BBB repair after stroke." (PMID 37968698, 2023).